PDHA2 (pyruvate dehydrogenase E1 subunit alpha 2)
Description:
Together with PDHB forms the heterotetrameric E1 subunit of the pyruvate dehydrogenase (PDH) complex in testis. The PDH complex catalyzes the overall conversion of pyruvate to acetyl-CoA and CO(2), and thereby links cytoplasmic glycolysis and the mitochondrial tricarboxylic acid (TCA) cycle (Probable). It contains multiple copies of three enzymatic components: pyruvate dehydrogenase (E1), dihydrolipoamide acetyltransferase (E2) and dihydrolipoamide dehydrogenase (E3) (Probable). The E1 subunit catalyzes both the thiamine pyrophosphate (TPP)-dependent decarboxylation of pyruvate and the reductive acetylation of a lipoyl group covalently linked to the lipoyl-bearing domains of E2.
Synonyms: PDHAL; SPGF70
Tractability: PROTAC: ubiquitination databases record sites on it.
Target class: Enzyme; Oxidoreductase
Gene: Protein-coding gene on chromosome 4 (95,840,093 to 95,841,464, forward strand). Ensembl gene ENSG00000163114.
Subcellular location: Mitochondrion matrix
Subcellular location (Human Protein Atlas): Mitochondria; Nucleoli
Pathways (Reactome):
Metabolism: PDH complex synthesizes acetyl-CoA from PYR; Regulation of pyruvate dehydrogenase (PDH) complex
Signal Transduction: Signaling by Retinoic Acid
Gene Ontology:
Molecular function: protein binding; pyruvate dehydrogenase (acetyl-transferring) activity; oxidoreductase activity, acting on the aldehyde or oxo group of donors, disulfide as acceptor
Biological process: pyruvate decarboxylation to acetyl-CoA
Cellular component: mitochondrion; nucleus; pyruvate dehydrogenase complex; mitochondrial matrix
Genetic constraint (gnomAD): Loss-of-function variants: 0 observed, 1.86 expected, observed/expected ratio (o/e) 0, 90% interval 0 to 1.41. That is too few expected variants to judge how well the gene tolerates losing a copy. Missense variants: 533 observed, 522.97 expected, observed/expected ratio (o/e) 1.02, 90% interval 0.95 to 1.1. Synonymous variants: 188 observed, 198.12 expected, observed/expected ratio (o/e) 0.95, 90% interval 0.84 to 1.07.
Homologues: Orthologues: chimpanzee PDHA2 (99% identical), macaque PDHA2 (95% identical), rabbit PDHA2 (88% identical), tropical clawed frog pdha1 (77% identical), zebrafish pdha1a (76% identical), rat Pdha2 (75% identical), mouse Pdha2 (75% identical), zebrafish pdha1b (74% identical), Caenorhabditis elegans pdha-1 (57% identical), Drosophila melanogaster Pdha (56% identical), Drosophila melanogaster CG7024 (50% identical). Paralogues in human: PDHA1 (86% identical), BCKDHA (27% identical).
Diseases named in the same sentence as PDHA2 in open-access papers:
PDHA2 is named in the same sentence as 11 diseases in open-access papers, as found by Europe PMC text mining. Sharing a sentence is not in itself a finding about the gene and the disease. The quoted sentences say what the papers report.
male infertility (5 papers, 2018 to 2025). The inability of the male to effect fertilization of an ovum after a specified period of unprotected intercourse. "However, the role of PDC in fertility is unclear, although studies suggest that mutations and/or altered expression of PDHA2 correlate with male infertility in both humans and hamsters." (PMID 39973374, 2025). "Studies have identified PDHA2 as a potential new gene associated with male infertility." (PMID 39409733, 2024). "We show that PDHA2 knockout results in male infertility in mice, but meiotic DSBs in spermatocytes occur normally and are efficiently repaired." (PMID 39973374, 2025). "Mutations of PDHA2 (pyruvate dehydrogenase E1 subunit alpha 2), encoding a catalytic subunit of the pyruvate dehydrogenase complex (PDC), have been reported to be associated with male infertility in humans." (PMID 40679056, 2025). "The results of these experiments indicate that PDHA2 absence results in germ cell apoptosis, abnormal meiosis completion and azoospermia, leading to male infertility." (PMID 40679056, 2025). "It has been reported that deficiency of the genes with similar expression profile, such as Zmym3, Ku70, Fam46d, Pdha2, Tex101 and Spata19, etc. always resulted in spermatogenic problems leading to male infertility, thus validating the essential roles of these genes." (PMID 29563520, 2018). "This section will briefly highlight the role of the eight (TNP1, TNP2, PDHA2, LDHC, SPINK2, ODF1, ODF2, and PCDHB3) common DEGs in male infertility as obtained from our findings." (PMID 35207567, 2022).
Azoospermia (1 paper, 2025). Absence of any measurable level of sperm,whereby spermatozoa cannot be observed even after centrifugation of the semen pellet. "Here, we show that Pdha2 knockout (KO) mice exhibit azoospermia due to failure at the late pachytene-diplotene transition." (PMID 40679056, 2025). "Deletion of Pdha2 leads to azoospermia due to meiotic arrest at the late pachytene-diplotene stage transition." (PMID 40679056, 2025).
cervix adenocarcinoma (1 paper, 2012). "Accordingly, the various PDHA2 reporter plasmids and the parental pGL2-Basic vector were transfected into HeLa (cervix adenocarcinoma), NT2 (human teratocarcinoma) and SH-SY5Y (human neuroblastoma) cells, which do not normally express PDHA2 mRNA." (PMID 22675509, 2012).
melanoma (1 paper, 2012). A malignant, usually aggressive tumor composed of atypical, neoplastic melanocytes. "As we observed, PDHA2 is substantially down-regulated in VGP melanoma, which can be attributed to the increased level of acetyl-CoA." (PMID 22295108, 2012).
papilloma (1 paper, 2022). A benign epithelial neoplasm that projects above the surrounding epithelial surface and consists of villous or arborescent outgrowths of fibrovascular stroma. "The mRNA levels of prolyl 4-hydoxylases-1 (Pdha1) and -2 (Pdha2), the key enzymes in collagen biosynthesis, were also significantly downregulated in Itga11−/− papillomas." (PMID 36003785, 2022).
cancer (1 paper, 2021). A tumor composed of atypical neoplastic, often pleomorphic cells that invade other tissues. "Genes ADH1B and PDHA2 were differentially expressed in most of the 12 types of cancer and five pairs of genes exhibited consistent correlation changes (from strong correlations in normal controls to weak correlations in cancer patients) across all types of cancer." (PMID 34163562, 2021). "GenesADH1B and PDHA2 were differentially expressed in most ofthe 12 types of cancer." (PMID 34163562, 2021).
PDHA2 also shares sentences with these, for which no sentence is quoted: hepatocellular carcinoma (1 paper); Infertility (1); kidney disease (1); neuroblastoma (1); teratocarcinoma (1).